AR (androgen receptor)
Diseases named in the same sentence as AR in open-access papers (continued):
Sharing a sentence is not in itself a finding about the gene and the disease.
tumor (continued). "Most PCa cells, especially early PCa cells, are sensitive to androgens; however, during disease progression, cell populations differing in androgen sensitivity and AR dependency arise within a tumor cell population." (PMID 39768760, 2024). "The large number of tumors analyzed for several tumor categories enabled an analysis of the potential clinical significance of AR expression." (PMID 38790919, 2024). "Through in vivo experiments and analysis of human samples, AR signaling was suggested to affect the activity of tumor-infiltrating CD8+ T cells, resulting in men exhibiting lower antitumor immune activity." (PMID 38254871, 2024). "Although practically all patients initially experience tumor regression following AR-targeted therapy, the response is only transient, ultimately leading to metastatic castration-resistant prostate cancer (mCRPC), which remains uncurable." (PMID 38254784, 2024). "ERG, in concert with co-repressive proteins such as HDAC and EZH2, governs AR transcriptional activity, suppressing epithelial differentiation and fostering tumor progression." (PMID 38482016, 2024). "The ErbB signaling pathway has been reported to promote tumor growth by reactivating androgen receptor expression in patients with CRPC." (PMID 39075471, 2024). "This condition leads to tumour progression and the proliferation of malignant clones through either androgen receptor (AR) pathway reactivation or AR-independent pathways activation." (PMID 38254687, 2024). "ARD-61 is an extremely potent AR degrader and has also shown effectiveness in enzalutamide-resistant systems and two distinct xenograft tumor models derived from LNCaP and VCaP cells." (PMID 38675453, 2024). "Conversely, AhR can inhibit AR signaling through the recruitment of corepressors or the ubiquitin-proteasome pathway, accelerating AR degradation and reducing its transcriptional activity, potentially inhibiting tumor growth." (PMID 39184676, 2024). "This study expands our understanding of AR controlled exosomes secretion by AR-ligands and their protein content mediating tumor growth." (PMID 38589887, 2024). "NSD2-dependent AR sites distinctively harbor the chimeric FOXA1:AR half-motif, which exclusively comprise tumor-specific AR enhancer circuitries defined from patient specimens." (PMID 39251788, 2024). "Microscopic observation at magnifications of 40×, 100×, 200×, and 400× revealed that AR protein expression was almost undetectable in the tumor tissues of the CKS group." (PMID 39349354, 2024). "In the compound mouse model, selective deletion of stromal AR expression in Gli1-lineage cells impaired transgenic Myc-induced prostatic epithelial oncogenesis and tumor development." (PMID 39369165, 2024). "Consistent with bicalutamide, enzalutamide also decreases cell proliferation, increases apoptosis, and reduces the tumor growth of AR-positive TNBC cell lines and xenografts." (PMID 38339092, 2024). "Given the frequent and often high-level AR expression in many other tumor types, it is obvious to consider AR targeting therapies for these tumors." (PMID 38790919, 2024). "Multiple early patient studies demonstrated widespread nuclear AR expression in primary OCs (from 43.7% to 90% of tested tumours)." (PMID 38994724, 2024). "CDK8/19i treatment also suppressed tumor growth in 3 AR-positive PDX models derived from PCa patients, at least 2 of whom failed ADT and chemotherapy." (PMID 38546787, 2024). "Further investigations revealed that α-mangostin treatment led to decreased expression of genes regulated by AR and AR-V7 in tumor tissues." (PMID 39199550, 2024). "Further investigation of the cistromic interplay between KDM4B, GATA3 and AR in the breast is required to definitively identify how KDM4B contributes to AR-mediated luminal programs and tumor suppression in the breast." (PMID 38317241, 2024).
tumor (continued). "Here, we lay out the epidemiological context of sex disparity in cancer and then review the current literature on how AR signalling contributes to such observation via altered tumour development and immunology." (PMID 38863718, 2024). "Modern pharmacological research demonstrated that AR has many pharmacological activities, including immunomodulatory activity, anti-tumor, anti-inflammation, anti-aging, and anti-heart failure." (PMID 39215362, 2024). "A similar case can be seen in the lncRNA HOTAIR, which is also an AR‐repressed gene that prevents AR protein from undergoing ubiquitin‐mediated degradation in CRPC tumours but avoids being repressed." (PMID 38214432, 2024). "More recently, the determination of androgen hormone receptor (AR) expression has provided an even wider perspective on the biological tumor profile, uncovering new therapeutic potentials." (PMID 39768587, 2024). "In ER-positive breast cancer, AR behaves as a tumor suppressor, with its function being opposite to ER." (PMID 38339092, 2024). "Our results provide an important basis for further research on the significance of the AR gene in clinical monitoring of PCa and the potential of EV DNA as a new tumour marker." (PMID 39535155, 2024). "Pathological classification of TNBC using EGFR, CK5/6, AR, cell-adhesion molecules, and tumor infiltrating lymphocytes (TIL) has been suggested to optimize treatment of TNBC." (PMID 37934318, 2024). "On the other hand, in cases where resistance to endocrine therapy develops, and thus ERα activity is modified, AR switches its function from tumor suppressor to oncogenic in order to promote cell growth and survival." (PMID 39338407, 2024). "AR-targeted therapy using androgen deprivation therapy in combination with AR antagonists is commonly used to block AR activity and slowing-down tumor growth." (PMID 39668349, 2024). "As per the multivariate Cox analysis of TCGA data, the tumor size (T), prostate-specific antigen, Gleason score, FTO, and AR expression levels were all associated with PFS." (PMID 38384328, 2024). "Enhancer activity (H3K27ac ChIP-seq) confirms that AR binding patterns reflect active regulatory control at tumor- and normal-specific AR peaks." (PMID 39672812, 2024). "Our team recently showcased the promising anti-tumor efficacy of the PROTAC degrader targeting the mSWI/SNF ATPase subunit in preclinical models of AR-driven prostate cancer." (PMID 38328238, 2024). "Here, we show that tumor-specific AR enhancers are critically reliant on H3K36 dimethyltransferase activity of NSD2." (PMID 39251788, 2024). "A single dose of ARD-69 effectively reduced AR protein levels in tumor tissues that had been transplanted into mice." (PMID 37847340, 2024). "In cancer cells, activated Ack1 mediates the phosphorylation of Wwox protein that is thought to play an essential role in triggering the activation of the Akt pathway and androgen receptor (AR), leading to tumor growth." (PMID 39123481, 2024). "It has been reported that the anti-androgen therapy pressure exerted on the intrinsic cellular heterogeneity of PCa tissues led to the selection of tumour cells showing AR gene alterations or epigenetic perturbation of its regulated pathways." (PMID 38254687, 2024). "The patient was commenced on conventional androgen deprivation therapy (ADT) in the form of an LHRH agonist (Prostap; leuprorelin) and a short course of an AR antagonist (bicalutamide) to cover for tumour flare." (PMID 38667288, 2024). "The AR is a direct regulator of Tcf7, and its signalling induces the sex‐biased generation of the Tpex cell subset with impaired tumour control." (PMID 39169517, 2024). "In PCa, SPOP functions as a tumor-suppressor gene by promoting the degradation of multiple oncogenic substrates, including AR and ERG." (PMID 38339274, 2024). "Accumulating studies have revealed that AR expression has been upregulated, and androgen/AR signaling stimulated tumor growth and metastasis in OVC." (PMID 39077471, 2024).
tumor (continued). "Elevated AR abundance possibly facilitates heightened tumor progression and metastasis in spheroid tumors." (PMID 38632341, 2024). "The ability to evaluate the AR status in serum, plasma, or urine as well as circulating tumor cells (CTCs) suggests the use of AR expression as a biomarker for disease monitoring in real time." (PMID 37902839, 2024). "AR-V7 mRNA level was higher in patients with tumour size over 3 cm and AR-FL protein was higher in single tumours (p < 0,005)." (PMID 39083104, 2024). "In the initial phases of the disease, PC often relies on androgens, and surgical/chemical castration or AR antagonists are employed to deprive the tumor of AR activity." (PMID 38607017, 2024). "These agents effectively blocked testosterone and dihydrotestosterone (DHT) binding to AR, inhibiting receptor-mediated gene regulation and tumor growth." (PMID 39796704, 2024). "Preclinical studies have shown that AR activates many potential tumor-promoting signaling pathways and appears to substantially alter anti-tumor immunity." (PMID 38398136, 2024). "For example, the inhibition of KDM1A was observed to prevent pioneer factor FOXA1 from binding chromatin, thereby decreasing AR activity and suppressing tumor growth." (PMID 38254784, 2024). "The notable correlation observed between RFX6 and AR expression in PCa tissues underscores the importance of their interplay in influencing tumor growth and development." (PMID 38932472, 2024). "Recent developments in immune-oncology have shown important roles for AR signalling in regulating T cell responses to tumours and limiting the efficacy of checkpoint blockade through T cell exhaustion." (PMID 39232147, 2024). "Common biomarkers include Epidermal growth factor receptor, c-KIT and cytokeratins, Androgen receptor, Tumor-infiltrating lymphocytes, PD-L1/PD-1 expression, microRNAs, and long non-coding RNAs." (PMID 38857504, 2024). "As the most abundant cell population in various tumours, macrophages have the suppressive effect on the immune microenvironment, in addition to directly promoting AR signalling in PCa cells." (PMID 39138838, 2024). "Strikingly, motif analysis of the AR cistromes generated from patient specimens revealed the FOXA1:AR half-motif to be exclusively detected in the tumor-specific AR enhancer circuitries, with such chimeric motifs being essentially absent at normal AR sites." (PMID 39251788, 2024). "Extending to human tissues, IST5-002 down-regulated AR-FL and AR-V mRNA levels in six patient-derived clinical PCs cultured ex vivo in tumor explant cultures suggesting potential efficacy in clinical PC." (PMID 38416822, 2024). "Some studies reported that AR promotes BC tumor growth and metastasis while others reported that androgens primarily exhibit tumor suppressive effects." (PMID 38965614, 2024). "Most importantly, our data also show that—often at lower frequency—AR expression can also be found in a broad variety of other tumor types." (PMID 38790919, 2024). "AR can directly upregulate tumor-suppressor genes or upregulate the expression of tumor-suppressing proteins." (PMID 39768587, 2024). "First, cholesterol is a critical precursor for the synthesis of steroid hormones, including androgens, which sustains the activation of AR in tumour cells after castration therapy." (PMID 38969865, 2024). "The tumor cells also downregulated androgen receptor (AR) expression in stromal fibroblasts, while an adequate level of stromal AR expression is maintained in normal prostate homeostasis." (PMID 38322789, 2024). "AR positivity was found in 116 tumor types including 66 tumor types (46.8%) with ≥1 strongly positive tumor." (PMID 38790919, 2024). "This underscores the continued importance of AR and its downstream signaling pathways in tumor growth." (PMID 40353136, 2024). "The objective of the current standard-of-care therapies is to inhibit the androgen receptor (AR) signalling axis, a major driver of tumour growth and disease progression." (PMID 39025852, 2024).
tumor (continued). "It would be interesting for future studies to investigate the clinical significance of AR expression in all these different tumor types that recurrently showed positive AR immunostaining." (PMID 38790919, 2024). "Oral administration of ARD-1676 effectively reduces the AR protein level in the VCaP tumor tissue in mice." (PMID 38675453, 2024). "Oral administration of bavdegalutamide is effective at diminishing AR protein levels in VCaP and LNCaP xenograft tumor tissues." (PMID 38675453, 2024). "Selective targeting of PARP-2 inhibited AR-positive prostate cancer cell growth and tumor growth in vivo." (PMID 39201718, 2024). "ZMIZ2 enhances the transcriptional activity of androgen receptor(AR), which is highly expressed in HCC and is associated with increased tumor recurrence and decreased overall survival." (PMID 38254216, 2024). "Orchiectomy provides protection against tumor induction, and T seems to exert a protective effect mediated by the membrane androgen receptor or its conversion to E2." (PMID 38867310, 2024). "PROTAC canalso be used to target proteins that are involved in tumor growth,such as the androgen receptor and the EGFR." (PMID 38990186, 2024). "We further confirmed the overexpression of LINC01126 in CRPC cell lines and AR‐dependent CRPC tumours with qRT‐PCR and RNA ISH assays." (PMID 38214432, 2024). "Future studies analyzing AR protein expression and AR transcriptional activity from tumor tissues can provide insights into these observations in EA men." (PMID 38566104, 2024). "Another study revealed that CRY1, a tumor-specific AR signaling pathway target gene, is involved in androgen-regulated DNA repair and plays an important role in the growth of androgen-resistant prostate cancer (CRPC)." (PMID 39011396, 2024). "Recently, it has been shown that the newly developed RORγ-antagonist, XY018, was able to inhibit the growth of androgen receptor-positive prostate cancer via downregulation of RORγ in tumor cells." (PMID 38030791, 2024). "Analysis of consensus genes present in all tumour samples analysed revealed significant enrichment of epigenetic, AR, and NEPC gene signatures, while WNT and DNA damage repair signalling displayed a trend for increased enrichment." (PMID 38667288, 2024). "AR status was available for 15/18 patients; positive tumour staining for AR was seen in 12/15 cases, and all but one of these had received prior AR-directed treatment with bicalutamide with or without a luteinising hormone-releasing hormone (LHRH) agonist." (PMID 39330047, 2024). "The androgen receptor (AR) is highly expressed in these subtypes as well and is shown to impact tumor growth and decrease immune infiltration." (PMID 39684829, 2024). "BAT resulted in a significant decrease in the mitotic index of tumor cells, along with a notable increase in the cell death index and AR in mitosis compared with the control group." (PMID 38255286, 2024). "The dual role of AhR in modulating AR signaling complicates therapeutic strategies, necessitating personalized approaches based on the unique characteristics of each patient's tumor." (PMID 39184676, 2024). "Blocking AR signaling can sensitize the tumor-bearing host to effective checkpoint blockade by directly enhancing CD8 T cell function, preventing T cell exhaustion, and improving responsiveness to PD-1 targeted therapy via increased IFNγ expression." (PMID 38698844, 2024). "By 8–10 weeks, primary and metastatic tumor cells were mostly AR− and ASCL1+ with heterogenous KRT8 and E-cadherin expression." (PMID 39394434, 2024). "At diagnosis PC is an androgen-dependent disease, relying on ligand-mediated signaling via the androgen receptor (AR) for tumor growth." (PMID 39195285, 2024). "It was observed that high FATS expression correlates with increased androgen receptor expression (p = 0.019), tumor-infiltrating lymphocytes (p = 0.029), and ypTNM stage (p < 0.05)." (PMID 39550407, 2024).
tumor (continued). "Most of the patients showed AR expression, and it was mainly located in the cytoplasm, as well as in the nucleus of tumor cells." (PMID 38233838, 2024). "Our previous study demonstrated that tumor suppressive miR-99b-5p negatively regulates the expression of androgen receptor (AR) and mTOR, potentially serving as a therapeutic agent for aggressive PCa." (PMID 38792011, 2024). "Of particular interest is the high expression of TROP2 in AR-/NE- tumors, a molecular tumor subtype for which there are presently only limited therapeutic options." (PMID 38760413, 2024). "The results support our above observation of tumor suppression by AR restoration in cell line 1508, whereas in cell line 1258, AR restoration increased the degree of tumor aggressiveness." (PMID 39201315, 2024). "We have previously shown that on PC patients, positive SRSF-1 expression was associated with AR, Ki-67, IR-α, and microvascular density, indicating a potential role of SRSF-1 in driving tumor aggressiveness." (PMID 38731981, 2024). "Recent studies investigating molecular and histologic profiles of SDC report that the androgen receptor (AR) signaling pathway is involved in tumor progression and aggressiveness." (PMID 38539538, 2024). "For example, AhR activation can lead to the ubiquitination and degradation of AR, reducing its transcriptional activity and potentially inhibiting tumor growth." (PMID 39184676, 2024). "In particular, C-terminal Binding Protein 2 (CTBP2), an OCT1/AR target gene, was correlated with poor prognosis and immunosuppressive effects in the tumor microenvironment." (PMID 38698344, 2024). "In preclinical models, when confronted with elevated AR expression, the administration of testosterone to attain supraphysiological serum levels paradoxically leads to PCa cell death and tumor regression." (PMID 38255286, 2024). "AR expression of the primary tumor (PT) was assessed by immunohistochemistry on formalin-fixed, paraffin-embedded (FFPE) tumor sections from core biopsies and surgical specimens." (PMID 37902839, 2024). "AR-targeted therapy using androgen deprivation therapy in combination with AR antagonists is commonly used to block AR activity to slow tumor growth." (PMID 38902772, 2024). "The tumor alters several signaling pathways for achieving invasive and aggressive capabilities, such as the Androgen receptor (AR) pathway and the EMT process." (PMID 38398019, 2024). "Promoter hypermethylation can lead to the silencing of not only tumor-suppressor genes but also key receptors, such as AR and ESR1." (PMID 38339274, 2024). "In lung metastases of monolayer tumors, 60% of the tumor cells showed strong nuclear staining of the AR in contrast to 70% in lung metastases from spheroid tumors (p = 0.5)." (PMID 38632341, 2024). "Degarelix treatment increased the fraction of NEPC tumor area and ASCL1+ tumor cells and decreased the fraction of AR+ tumor cells relative to vehicle treated RPM SQ tumors." (PMID 39394434, 2024). "Together, these studies uncover AR as a sex-differentiated tumor regulator that modulates antitumor immune activity." (PMID 38254871, 2024). "While these drugs initially have a profound effect in slowing AR-driven tumor progression in most patients, the antitumor effects are often short-lived, and resistance eventually occurs." (PMID 38337427, 2024). "Immunohistochemical staining of a TNBC tissue microarray containing 165 tumor specimens suggests that AR is positively correlated with tumor size, lymphatic metastasis, and high histological grade and negatively associated with GPER expression in TNBC." (PMID 38476263, 2024). "AR signaling promotes tumor growth by stimulating genes involved in cell proliferation, survival, and angiogenesis." (PMID 39342345, 2024).